SLC25A1 (solute carrier family 25 member 1)
Diseases named in the same sentence as SLC25A1 in open-access papers (continued):
Sharing a sentence is not in itself a finding about the gene and the disease.
cancer (continued). "Pharmacological targeting of SLC25A1 and ACLY sensitizes cancer cells to ferroptosis and inhibits tumor growth both in vitro and in vivo, suggesting that an in-depth study of this pathway may provide a new strategy for ferroptosis-targeted cancer treatment." (PMID 39881208, 2025). "In conclusion, the present study describes the synergistic effect of αKG supplementation in combination with SLC25A1 inhibition on cellular and mitochondrial function, creating a cellular demand for NAD to balance cellular activities important for cancer cell survival and radiosensitization." (PMID 38225236, 2024). "Our observations suggest that decreasing levels of NAD+, NADH, NADP+ and NADPH may become critical for cell survival upon inhibition of SLC25A1 in NCI-H460 and A549 cancer cells." (PMID 38225236, 2024). "Following that, we searched the relationship between SLC25A1 expression and infiltration level of 6 immune cell types (CD4 + T cells, CD8 + T cells, neutrophils, myeloid dendritic cells, macrophage, and B cells) in pan-cancer from the TIMER database." (PMID 37981593, 2023). "Hence, we analyzed the correlation between SLC25A1 expression and MSI/TMB in diverse cancer types of TCGA." (PMID 37981593, 2023). "Among the 33 tumors, three forms of cancer showed downregulation of SLC25A1 in tumor tissues compared to non-tumor tissues (BRCA, LAML, and THCA)." (PMID 37981593, 2023). "Among the 224 differently regulated proteins that are more abundant in male D sites are tricarboxylate transport protein (SLC25A1), proteasome β-4 subunit (PSMB4), and type II cytoskeletal 2 oral keratin (KRT76), all with known roles in cancer (expression profiles)." (PMID 35566209, 2022). "In this regard, the importance of the mitochondrial citrate carrier (SLC25A1) has recently emerged in tumor progression, cancer stemness, and resistance to therapy; additionally, the specific SLC25A1 inhibitor benzenetricarboxylate (BTA) has been proven to exert a promising anticancer activity." (PMID 32825551, 2020). "Mechanistically, treatment with the SLC25A1-inhibitor BTA disturbed cellular redox homeostasis by decreasing NADPH/GSH levels but also affected mitochondrial metabolism and cellular energy provision thereby reducing cancer cell survival." (PMID 29888201, 2018). "Inhibition of SLC25A1 by 1,2,3-benzene-tricarboxylic acid (BTA) disturbed cellular and mitochondrial redox homeostasis, lowered mitochondrial metabolism, and reduced metabolic flexibility of cancer cells." (PMID 29888201, 2018). "In addition, our results clearly demonstrate that inhibition of SLC25A1 by the small molecule inhibitors BTA and CNASB is suited to increase radiosensitivity of NCI-H460 cancer cells exposed to acute or chronic cycling hypoxia." (PMID 29888201, 2018). "However, to our knowledge, no research has evaluated the relationship between SLC25A1 expression and cancer immunology." (PMID 37981593, 2023). "Interestingly, no significant negative correlation between MSI/TMB and SLC25A1 expression was observed in all these types of cancer." (PMID 37981593, 2023). "Thus, SLC25A1 inhibition is suited for pharmacologic disturbance of HR repair and thereby induces radiosensitivity in combination with clinically relevant DSB repair inhibitors in cancer cells." (PMID 35869047, 2022). "So far, our data indicated that pharmacologic inhibition of SLC25A1 by BTA or CNASB increases radiosensitivity of oxic and anoxia-tolerant NCI-H460 cancer cells and that disturbance of the redox homeostasis and of metabolic flexibility might participate in the radiosensitizing effects." (PMID 29888201, 2018). "Thus, SLC25A1 and IDH2 might cooperate in adaptive metabolic processes that allow cancer cells to cope with the adverse conditions in the tumor microenvironment." (PMID 29888201, 2018).
tumor (26 papers, 2013 to 2026). "SLC25A1, a key member of the mitochondrial carrier protein family, assumes a pivotal position in maintaining cellular metabolic homeostasis, and its dysfunction is closely associated with metabolic disorders and tumor development 43-45." (PMID 41362733, 2026). "We also demonstrate that pharmacological blockade of SLC25A1 and ACLY increases cell susceptibility to ferroptosis and markedly enhances ferroptosis-induced tumor suppression." (PMID 39881208, 2025). "Knocking down SLC25A1 induces G1/S cell cycle arrest and apoptosis, significantly suppressing tumor growth in vitro and in vivo." (PMID 41020873, 2025). "Then, the relationship between SLC25A1 expression and tumor prognosis was checked based on GEO datasets." (PMID 37981593, 2023). "Its expression was observed significantly increase in the advanced stage (stage III/ IV) relative to early-stage (stage I/ II) in ACC, BRCA, KIRC, and TGCT, suggesting a role for SLC25A1 in tumor suppression." (PMID 37981593, 2023). "Stable knockdown of SLC25A1 by transfection with shRNA expression vector targeting SLC25A1 markedly decreased tumor growth rate and weight as compared to the control group." (PMID 34839347, 2021). "Here, we found that SLC25A1 expression was significantly increased in tumor samples of CRC as compared with paired normal samples, which is associated with poor survival in patients with CRC." (PMID 34839347, 2021). "Studies have shown that SLC25A1 is an essential component of the tumor cell metabolism and have enlightened novel mechanisms and therapeutic perspectives for the treatment of resistant non-small cell lung cancer tumors." (PMID 32455902, 2020). "It has been demonstrated that SLC25A1 plays a key role in the adaptive mechanisms that allow some tumor cells to acquire drug resistance." (PMID 32455902, 2020). "In this context, the recent finding that Slc25a1 plays a key role in the drug-induced metabolic switch that enables tumor cells to become resistant to cisplatin is of particular interest and in agreement with our observations." (PMID 31189116, 2019). "We have shown that SLC25A1 plays a key role in the adaptive mechanisms that allow some tumor cells to acquire drug resistance." (PMID 29651165, 2018). "In summary, our studies have shown that SLC25A1 is an essential component of the tumor cell metabolism and have enlightened novel mechanisms and therapeutic perspectives for the treatment of resistant NSCLC tumors." (PMID 29651165, 2018). "For this we measured the effects of the SLC25A1-inhibitor BTA on radiation-induced eradication of clonogenic tumor cells in long-term colony formation assays (delayed plating) upon treatment in combination with IR." (PMID 29888201, 2018). "Disruption of key mitochondrial molecular transport molecules, such as SCaMC-1, or SLC25A1, in proliferating cells has been suggested as a mitochondrial specific approach to tumor treatment." (PMID 23509753, 2013). "Moreover, SLC25A1 has been reported to be functionally involved in tumor stemness, radioresistance, and chemotherapy resistance by reprogramming energy metabolism, maintaining redox homeostasis, and supporting lipid biosynthesis." (PMID 37981593, 2023). "This study shed new light on the role of SLC25A1 in tumor immunity." (PMID 37981593, 2023). "Moreover, SLC25A1 was positively associated with MSI, TMB, and CD276 and tightly correlated with tumor-infiltrating immune cells." (PMID 37981593, 2023). "However, HR-ness phenotype induced by SLC25A1 inhibition significantly reduced tumor growth in combination with PARPi, thus blocking the major DNA damage repairing pathways upon IR-treatment." (PMID 35869047, 2022). "Additionally, tumor tissues developed from SLC25A1 knockdown LS174T cells had significantly lower expression of Ki67 than the control group." (PMID 34839347, 2021).
tumor (continued). "Considering that de novo fatty acid synthesis plays an important role in meeting the biosynthetic demands for tumor cell growth, we hypothesized that upregulation of SLC25A1 might promote tumor growth of CRC by increasing fatty acid synthesis." (PMID 34839347, 2021). "In addition, injection of SLC25A1 knockdown LS174T cells into BALB/c mice further supported the role of SLC25A1 in the promotion of tumor growth in vivo." (PMID 34839347, 2021). "Finally, we and others have shown that Slc25a1 plays an important role in the metabolic rewiring of tumor cells, in chemotherapy resistance and as a mediator of inflammatory signals." (PMID 31959914, 2020). "SLC25A1 maintains mitochondrial integrity and bioenergetics in tumor cells." (PMID 32265986, 2020). "Indeed, we have documented that inhibition of SLC25A1 in tumor cells impairs OXPHOS, albeit with yet unknown molecular mechanisms." (PMID 39733217, 2025). "Therefore, further studies focusing on SLC25A1 expression and tumor immunity may contribute to not only the understanding of existing immunotherapeutic approaches but also the development of novel immune-targeted treatment strategies." (PMID 37981593, 2023). "Correlation analysis between SLC25A1 expression and the clinicopathological features of CRC patients revealed that SLC25A1 expression was significantly positively correlated with tumor size." (PMID 34839347, 2021). "We have previously demonstrated that SLC25A1 (CIC) promotes tumorigenesis, while its inhibition blunts tumor growth." (PMID 24681808, 2014). "Consistently, immunohistochemistry (IHC) staining assay in another 268 CRC cohort also showed significantly higher SLC25A1 protein level in the tumor tissues than in the matched non-tumor tissues." (PMID 34839347, 2021). "SLC25A1 is regulated by SREBP-1 and plays an important role in inflammation and tumor growth." (PMID 29784041, 2018). "Moreover, we were able to validate the expression of 16/57 differentially expressed proteins in MDCKYBX1 tumour xenografts, some of which were mitochondrial (ACADSB, SLC25A1, IARS2, and OAT)." (PMID 25980435, 2015). "In addition, as we observed previously in tumor cells, MEFs cells lacking SLC25A1 also prominently turned on glycolysis, which consumes NAD+ because many glycolytic enzymes use NAD+ as a co-factor." (PMID 39733217, 2025). "In addition, SCT treatment could upregulate ACLY gene expression but did not affect citrate synthesis (CS) or mitochondrial citrate carrier SLC25A1 expression in MCF7 and HCT116 tumor cells." (PMID 34747157, 2022). "The finding that CTPI-2 blunts proliferation in non-CSCs, although to a significantly lesser extent relative to CSCs, may indicate that SLC25A1 is not a specific target for CSCs, which represent a discrete tumor sub-population." (PMID 29651165, 2018). "Detection of SLC25A1 expression in tumor tissues and matched adjacent non-tumor tissues from 30 CRC patients by qRT-PCR analysis also indicated that the mRNA levels of SLC25A1 were significantly higher in CRC samples than in adjacent non-tumor tissues." (PMID 34839347, 2021).
infection (4 papers, 2021 to 2023). The state of being infected such as from the introduction of a foreign agent such as serum, vaccine, antigenic substance or organism. "In first infection, spleen monocytes primarily upregulate a carrier protein (encoded by Slc25a1) whose major substrate is citrate, a metabolite known to accumulate in inflammatory macrophages." (PMID 33752799, 2021). "Interestingly, after infection with the mutant RSV virus, the observed increase in gene expression was in particular pronounced for genes encoding mitochondrial proteins (TOM40, SLC25A1), when compared to infection with wild-type RSV." (PMID 35216012, 2022). "Simultaneous infection with Idh3α shRNA and Slc25a1 shRNA induced citratemt accumulation in MLE12 cells and downregulated SP-C protein expression." (PMID 36443565, 2022).
metabolic disorder (2 papers, 2021 to 2026). "Mutations in SLC25A1 cause a rare, often fatal metabolic disorder characterized by neonatal epileptic encephalopathy." (PMID 34312306, 2021).
cardiovascular disease (1 paper, 2023). "In addition, previous research has shown that the expression of ferroptosis-related genes (RTN3, SLC25A1, and GPX4) in cardiovascular disease correlates with the serum HDL level." (PMID 38086802, 2023).
liver (1 paper, 2025). "To explore the role of SLC25A1 in modulating ferroptosis sensitivity in vivo, we generated liver-specific Slc25a1 knockdown (Slc25a1-KD) mice three weeks after tail vein injection using AAV8 virus and subsequently established a liver IRI model." (PMID 39881208, 2025).
mitochondrial disease (1 paper, 2023). "Notably, it is only specific “milder” genetic mutations to SLC25A1 and TEFM that cause CMS; other previously identified mutations are associated with more severe and classical mitochondrial disease." (PMID 37239850, 2023). "SLC25A1-related disease is typically associated with D2 and L2 hydroxyglutaric aciduria (D/L-2-HGA), a severe neurometabolic mitochondrial disease characterized by encephalopathy, severe muscle weakness, seizures, respiratory distress, psychomotor delay, and early death." (PMID 37239850, 2023).
psychiatric disorder (1 paper, 2018). A disorder characterized by behavioral and/or psychological abnormalities, often accompanied by physical symptoms. "The Slc25a1 gene is involved in a variety of cognitive and psychiatric disorders as well as in impaired neuromuscular disorders." (PMID 30537945, 2018).
SLC25A1 also shares sentences with these, for which no sentence is quoted: adenocarcinoma (2 papers); autism (2); hepatocellular carcinoma (2); acute myeloid leukemia (1); astrocytoma (1); atherosclerosis (1); Autoimmunity (1); brain cancer (1); cardiac disease (1); cardiomyopathies (1); CEDNIK syndrome (1); Cognitive impairment (1); colon adenocarcinoma (1); colorectal tumor (1); COVID-19 (1); diffuse large B-cell lymphoma (1); Encephalopathy (1); Epileptic encephalopathy (1); gastric cancer (1); genetic disorder (1); glioma (1); heart failure (1); Hepatic steatosis (1); large cell lung cancer (1); leukemia (1); lung squamous cell carcinoma (1); neurodevelopmental disorder (1); neuropathy (1); nonalcoholic fatty liver disease (1); Noonan syndrome (1).
A further 12 diseases each share a sentence with SLC25A1 in 1 paper.